CHEK2 (checkpoint kinase 2)
Description:
Serine/threonine-protein kinase which is required for checkpoint-mediated cell cycle arrest, activation of DNA repair and apoptosis in response to the presence of DNA double-strand breaks. May also negatively regulate cell cycle progression during unperturbed cell cycles. Following activation, phosphorylates numerous effectors preferentially at the consensus sequence [L-X-R-X-X-S/T]. Regulates cell cycle checkpoint arrest through phosphorylation of CDC25A, CDC25B and CDC25C, inhibiting their activity. Inhibition of CDC25 phosphatase activity leads to increased inhibitory tyrosine phosphorylation of CDK-cyclin complexes and blocks cell cycle progression. May also phosphorylate NEK6 which is involved in G2/M cell cycle arrest. Regulates DNA repair through phosphorylation of BRCA2, enhancing the association of RAD51 with chromatin which promotes DNA repair by homologous recombination. Also stimulates the transcription of genes involved in DNA repair (including BRCA2) through the phosphorylation and activation of the transcription factor FOXM1. Also controls the transcription of pro-apoptotic genes through phosphorylation of the transcription factor E2F1. Tumor suppressor, it may also have a DNA damage-independent function in mitotic spindle assembly by phosphorylating BRCA1. Its absence may be a cause of the chromosomal instability observed in some cancer cells. Promotes the CCAR2-SIRT1 association and is required for CCAR2-mediated SIRT1 inhibition. Under oxidative stress, promotes ATG7 ubiquitination by phosphorylating the E3 ubiquitin ligase TRIM32 at 'Ser-55' leading to positive regulation of the autophagosme assembly. (Microbial infection) Phosphorylates herpes simplex virus 1/HHV-1 protein ICP0 and thus activates its SUMO-targeted ubiquitin ligase activity.
Synonyms: Hucds1; hCds1; CDS1; CHK2; RAD53; PP1425; bA444G7; LFS2; TPDS4
Tractability: Small molecule: a drug acting on it is in phase 2 or 3 trials; a structure with a bound ligand is known; a high-quality ligand is known; it has a high-quality binding pocket; it belongs to a druggable protein family. PROTAC: UniProt records ubiquitination sites on it; ubiquitination databases record sites on it; its protein half-life has been measured; a small molecule that binds it is known.
Target class: CAMK protein kinase group; Kinase; Protein Kinase; Enzyme; CAMK protein kinase RAD53 family
Chemical probes: CCT241533 (high quality), CCT241533, Chk2 Inhibitor, PD080744, PD083620, PD085222, PD085383
Gene: Protein-coding gene on chromosome 22 (28,687,738 to 28,742,422, reverse strand). Ensembl gene ENSG00000183765.
Subcellular location: Nucleus (Isoform 2); Nucleus (Isoform 4); Nucleus (Isoform 7); Nucleus (Isoform 9); Nucleus (Isoform 12); Nucleus, PML body; Nucleus, nucleoplasm
Subcellular location (Human Protein Atlas): Nucleoplasm; Golgi apparatus
Pathways (Reactome):
Cell Cycle: Chk1/Chk2(Cds1) mediated inactivation of Cyclin B:Cdk1 complex; G2/M DNA damage checkpoint; Ubiquitin-Mediated Degradation of Phosphorylated Cdc25A
DNA Repair: Recruitment and ATM-mediated phosphorylation of repair and signaling proteins at DNA double strand breaks
Gene Ontology:
Molecular function: identical protein binding; protein binding; protein homodimerization activity; protein kinase binding; protein serine kinase activity; protein serine/threonine kinase activity; ubiquitin protein ligase binding; ATP binding; protein kinase activity
Biological process: cellular response to stress; DNA damage response; double-strand break repair; G2/M transition of mitotic cell cycle; intrinsic apoptotic signaling pathway in response to DNA damage; mitotic intra-S DNA damage checkpoint signaling; mitotic spindle assembly; positive regulation of autophagosome assembly; positive regulation of DNA-templated transcription; protein autophosphorylation; protein catabolic process; protein phosphorylation; protein stabilization; regulation of autophagosome assembly; regulation of DNA-templated transcription; regulation of protein catabolic process; response to oxidative stress; response to starvation; signal transduction in response to DNA damage; DNA damage checkpoint signaling; mitotic DNA damage checkpoint signaling; replicative senescence
Cellular component: chromosome, telomeric region; nucleoplasm; PML body; cytoplasm; nucleus
Genetic constraint (gnomAD): Loss-of-function variants: 38 observed, 35.6 expected, observed/expected ratio (o/e) 1.07, 90% interval 0.82 to 1.4. The upper end of that interval is the gene's LOEUF score, 1.4, which puts it in group 5 of 6, group 1 being the genes least tolerant of losing a copy. Missense variants: 486 observed, 484.99 expected, observed/expected ratio (o/e) 1, 90% interval 0.93 to 1.08. Synonymous variants: 148 observed, 179.63 expected, observed/expected ratio (o/e) 0.82, 90% interval 0.72 to 0.94.
Gene-disease validity (ClinGen):
ClinGen rates the evidence that CHEK2 causes each of these diseases.
CHEK2-related cancer predisposition (autosomal dominant): Definitive.
hereditary nonpolyposis colon cancer (autosomal dominant): Limited.
familial ovarian cancer (autosomal dominant): Refuted. An instance of ovarian cancer that is caused by an inherited modification of the individual's genome.
Cancer hallmarks: genome instability and mutations (suppresses); escaping programmed cell death (suppresses)
Homologues: Orthologues: chimpanzee CHEK2 (99% identical), macaque CHEK2 (98% identical), rabbit CHEK2 (89% identical), dog CHEK2 (89% identical), pig CHEK2 (88% identical), guinea pig CHEK2 (87% identical), rat Chek2 (84% identical), mouse Chek2 (83% identical), tropical clawed frog chek2 (60% identical), zebrafish chek2 (49% identical), Drosophila melanogaster lok (32% identical), Caenorhabditis elegans chk-2 (28% identical), and 1 more.
Diseases named in the same sentence as CHEK2 in open-access papers:
CHEK2 is named in the same sentence as 324 diseases in open-access papers, as found by Europe PMC text mining. Sharing a sentence is not in itself a finding about the gene and the disease. The quoted sentences say what the papers report.
breast cancer (684 papers, 2001 to 2026). A primary or metastatic malignant neoplasm involving the breast. "In 2023, the National Comprehensive Cancer Network® (NCCN®) updated its guidelines for managing breast cancer risk in patients with a CHEK2 p.I157T variant, recommending de-escalation of enhanced screening based on this variant alone." (PMID 41756456, 2026). "The lifetime breast cancer risk conferred by CHEK2 variants is generally considered moderate, corresponding to an approximately 1.5- to fourfold increase compared with the general population." (PMID 41528496, 2026). "In our study, one of the patients developed breast cancer as a third tumor, and a CHEK2 mutation was detected." (PMID 39860595, 2025). "Conversely, BRCA2, ATM, PALB2, and CHEK2 were more commonly associated with later-onset breast cancer, for which the penetrance estimates ranged from 19% to 31% by age 60 years." (PMID 39858629, 2025). "We also meta-analyzed the results from previous studies and our own on prognosis in CHEK2 c.1100delC-associated breast cancer patients." (PMID 41314031, 2025). "Germline CHEK2 c.1100delC-associated breast cancer (BC) patients have been reported with worse prognosis than patients without the variant." (PMID 41314031, 2025). "The odds ratio was the highest for women with a CHEK2 truncating mutation and family history of breast cancer (OR = 4.2, 95%CI 1.3–10.8, p = 0.01)." (PMID 40770660, 2025). "This is consistent with the evidence that breast tumors which arise in carriers of CHEK2 mutations seem to be similar to those of breast cancers in the population at large." (PMID 40770660, 2025). "In contrast, germline CHEK2 mutations predispose human females to the development of breast cancer, whereas in lung tissue mechanisms compensating CHEK2 inactivation have evolved." (PMID 40072091, 2025). "EI_1103 has a sister with breast cancer and a brother with prostate cancer, both of whom carry the CHEK2 p.(Arg117Gly) variant." (PMID 40446793, 2025). "Biallelic CHEK2 PVs are associated with specific cancer phenotypes, including early age at onset of breast cancers." (PMID 39745704, 2025). "Germline pathogenic variants of CHEK2 are associated with reduced overall survival in breast cancer patients." (PMID 40563612, 2025). "We observed that the DCIS risk for a woman with a CHEK2 mutation and a family history of breast cancer was greater (OR = 2.3, p = 0.003) than that of a CHEK2 mutation carrier who has no family history of breast cancer (OR = 1.4, p = 0.06)." (PMID 40770660, 2025). "For CHEK2 P/LP variants, the homozygous state confers a higher risk of breast cancer than the heterozygous state." (PMID 39858629, 2025). "For other P/LP CHEK2 variants, the frequency of breast cancer was 21% (9/36) and prostate cancer 5% (2/36)." (PMID 40335619, 2025). "Multiple other players from the DDR pathway, including PALB2, ATM, and CHEK2, are also connected to breast cancer predisposition, although with lower risk." (PMID 40009290, 2025). "By impairing the repair of crucial DNA lesions, functional polymorphisms in XRCC1, XPD, and CHEK2 contribute to the development and severity of breast cancer." (PMID 40507526, 2025). "Breast cancer was most frequent among individuals with 2 PVs in CHEK2 (100%) followed by those with PV and LR variant (86.7%), a monoallelic PV (67.1%), 2 LR variants (60.0%), a monoallelic LR variant (57.5%), and WT (52.7%)." (PMID 39745704, 2025). "Typically, CHEK2 PVs are associated with moderate risk for breast cancers, conferring odds ratios (ORs) of 2- to 3-fold." (PMID 39745704, 2025). "Variants in the CHEK2 gene were first reported as truncating CHEK2 mutations (c.1100delC) that confer a greater than twofold increase in the risk of breast cancer." (PMID 40283643, 2025). "Carriers of germline mutations in CHEK2 have an estimated 25% to 30% lifetime probability of developing breast cancer, which is associated with a moderate risk." (PMID 40507526, 2025).
breast cancer (continued). "After meta-analyzing these results with the results of our current study, a significant worse breast cancer-specific survival in CHEK2 c.1100delC-associated breast cancer patients (RR = 1.29; 95 %CI = 1.06–1.58) remained compared to non-carriers." (PMID 41314031, 2025). "In most breast cancer susceptibility genes, Polish common founder mutations are present, including BRCA1, BRCA2, PALB2, and CHEK2, which constitute the majority (>80%) of all mutations detected in these genes in Polish women with breast cancer." (PMID 40649769, 2025). "CHEK2 LR variants (p.I157T, p.S428F, and p.T476M) appear to be more penetrant for any cancer, multiple primary cancers, breast cancer, and bilateral breast cancer when combined with a CHEK2 PV." (PMID 39745704, 2025). "Breast cancer was the first malignancy to be directly linked to germline CHEK2 variants, with multiple studies having shown that the c.1100delC mutation confers increased susceptibility to breast cancer." (PMID 40492861, 2025). "Third, we compared the prognosis in CHEK2 c.1100delC-associated breast cancer patients with the prognosis of patients who had an a-priori higher than average risk for breast cancer since they had an indication for genetic testing." (PMID 41314031, 2025). "Of note, the risk was highest for patients with a CHEK2 truncating mutation and a positive family history of breast cancer (OR = 4.2, p = 0.01)." (PMID 40770660, 2025). "In studies from China and Turkey, CHEK2 p.(Tyr390 Cys) missense variant was associated with breast cancer and was predicted to be most likely deleterious by Align-GVGD and SIFT and probably damaging by Poly-Phen2." (PMID 40448797, 2025). "We also checked the effect of a positive family history of breast cancer on DCIS risk among CHEK2 mutation carriers." (PMID 40770660, 2025). "Published reports have also documented cases of co-occurrence of breast cancer with CHEK2 mutations and pNENs in two sisters." (PMID 41294693, 2025). "CHEK2 c.1100delC heterozygotes have an increased risk of breast cancer and contralateral breast cancer." (PMID 41314031, 2025). "The risk was highest for carriers of CHEK2 truncating mutations with a family history of breast cancer (OR = 4.2, p = 0.01)." (PMID 40770660, 2025). "Cell cycle checkpoint kinase 2 (CHEK2) is a crucial element in the DNA damage response pathway and is linked to an increased risk of various cancers, including rhabdomyosarcoma and breast cancer." (PMID 39860595, 2025). "CHEK2 is a known breast cancer susceptibility gene that usually causes a moderate risk of breast cancer, and its truncating variants have been associated with a 2- to 3-fold risk of breast cancer." (PMID 39272813, 2024). "Research on breast cancer has indicated that pathogenic variants of CHEK2 are significantly less frequent in blacks compared to whites." (PMID 39541191, 2024). "Beyond CHEK2 GPVs, multiple factors are used to estimate breast cancer risk using programs such as CanRisk, including family history, hormonal and lifestyle factors, breast density, and polygenic risk scores." (PMID 39062660, 2024). "Overall, the likelihood of compound CHEK2 heterozygosity or the combination of CHEK2 c.1100delC and other pathogenic variants in one of the breast cancer-associated genes is small." (PMID 39384226, 2024). "CHEK2 variant rs587782401 has been associated with breast cancer, and it has been classified as likely pathogenic in ClinVar." (PMID 39272813, 2024). "A study investigating CHEK2 germline variants identified an association of the immunophenotypic molecular subtypes of breast cancer with the type of the genetic variant." (PMID 38978731, 2024). "Among the 12 male breast cancer patients in our cohort, we identified pathogenic variants in CHEK2 (c.846+1G>C) and PALB2 (c.758dup)." (PMID 39590369, 2024).
breast cancer (continued). "According to the NCCN guidelines v2.2024 (27 September 2023), germline PVs in the genes ATM, BARD1, RAD51C, RAD51D, NF1, and CHEK2 confer an absolute breast cancer risk between 17% and 40%." (PMID 38893140, 2024). "Our results from all-comers population genetic screening confirmed that rare pLOF variants in BRCA1, BRCA2, PALB2, ATM, and CHEK2 confer significant risk to breast cancer in the overall population." (PMID 39669587, 2024). "CHEK2 variants have been associated with a higher risk of bilateral breast cancer, which was the case with this patient as well." (PMID 39272813, 2024). "With this cohort, we ultimately aim to study the impact of CHEK2 c.1100delC on cancer risk prediction and surveillance, and treatment of breast cancer and prognosis within CHEK2 c.1100delC families." (PMID 39384226, 2024). "Individuals who inherit specific variants in the CHEK2 gene, for example, have increased risk of developing breast cancer and other cancers." (PMID 39146382, 2024). "Given the suggestion from a recent phase 2 clinical trial that CHEK2-associated breast cancers respond less well to poly-adenosine diphosphate ribose polymerase inhibitors, there is the future potential for knowledge of CHEK2 genotype to inform therapy." (PMID 39642869, 2024). "The 1100delC mutation in CHEK2 has been found to increase the risk of breast cancer two-fold in women and ten-fold in men." (PMID 38927753, 2024). "Individuals with biallelic gPVs in CHEK2 are, next to breast cancer, likely also at increased risk for other primary cancers." (PMID 38848470, 2024). "The probability of breast cancer diagnosis at age 70 in individuals with a pathogenic variant in ATM of CHEK2 and in the top 50% of the PRS distribution was 39.2%, whereas those in the bottom 50% of the PRS distribution had a risk of only 14.4%." (PMID 39669587, 2024). "Yet the lower risks of breast cancer observed for the missense CHEK2 I157T and S438F variants cannot be presumed for other missense variants." (PMID 39062660, 2024). "We identified three CHEK2 variants, including the pathogenic c.1100del variant, which is known to confer a greater than twofold increased breast cancer risk." (PMID 39590369, 2024). "Germline pathogenic variants in CHEK2 have been reported to be associated with an increased risk of breast cancer, thyroid cancer, and kidney cancer and possibly inform colorectal cancer risk." (PMID 39594831, 2024). "A study of 844 carriers of a CHEK2 PV found an average lifetime breast cancer risk close to the population level (14.3%) in the 20% of carriers with the lowest PRS and a high risk (32.6% lifetime risk) in the same proportion of women with the highest PRS." (PMID 39107016, 2024). "Having a breast cancer case in families with an ATM or CHEK2 variant is a prerequisite in the Netherlands for performing genetic testing in relatives, as it would otherwise not lead to any preventive options in relatives." (PMID 38722431, 2024). "The current study sought to compare cancer risk management for breast cancer among females with CHEK2 1100delC and CHEK2 I157T GPVs." (PMID 39062660, 2024). "Breast cancer (BC) risks imparted by CHEK2 c.1100delC (“1100delC”) germline pathogenic/likely pathogenic variant (GPV) are 20–30%, compared to CHEK2 c.470T>C (“I157T”) GPV with <20%, leading to different breast screening recommendations through MRI." (PMID 39062660, 2024). "Women with the heterozygous founder mutation CHEK2 c.1100delC, which leads to a protein truncation in the kinase domain, have a 2-3-fold increased risk of developing breast cancer." (PMID 39146382, 2024). "Deleterious germline variants in ATM and CHEK2 have been associated with a moderately increased risk of breast cancer." (PMID 39209703, 2024). "The odds ratios we observed for HiQ-damaging and HiQ-tolerated variants are each similar to the confidence interval for breast cancer odds ratio (1.2–1.77) reported recently for CHEK2 missense variants in an overlapping cohort." (PMID 39642869, 2024).